CCNE1 (cyclin E1)
Diseases named in the same sentence as CCNE1 in open-access papers (continued):
Sharing a sentence is not in itself a finding about the gene and the disease.
tumor (continued). "It is reported that miR-107 can target CCNE1 to inhibit OC cell cycle progression and proliferation, which is consistent with our finding that miR-107 shows the tumor-suppressing effects." (PMID 33926489, 2021). "Specific cyclin genes such as Ccna2, Ccnb1, Ccnb2, and Ccne1 encoding CYCLIN A2, B1, B2, and E1, respectively, were also upregulated in MMTV-R26Met tumours." (PMID 34646365, 2021). "DNA obtained from tissue with 70% tumor content was known to harbor 37 copies of CCNE1 (CNA), TSC1_c.2065C>T at 47% (SNA) and FANCI_ c.1641_1642delTA (small indel) at 3.7% VAF." (PMID 33556149, 2021). "Over-expression of Cyclin E1 during hepatocarcinogenesis modulates several distinct biological processes such as proliferation, DNA damage response, stemness, invasion and the tumour microenvironment." (PMID 34830835, 2021). "Another study has clarified that hsa_circ_0062389/miR-103a-3p/CCNE1 axis is beneficial for tumor formation in NSCLC." (PMID 34787049, 2021). "Tumor weight determination in the two siRNA-administered groups indicated that the si-CCNE1 group showed significantly decreased tumor growth than the control group (452.8 ± 274.6 vs. 789.9 ± 129.0, p = 0.013)." (PMID 34070839, 2021). "We investigated a potential relationship between the histological HCC grade (serving as a measure for differentiation status and malignancy of tumours) and the level of CCNE1 and CDK2 expression." (PMID 34830835, 2021). "We found 15 cell cycle regulatory genes (E2F targets or G2M checkpoint Hallmark genes) upregulated in female Ctnnb1 tumours compared to Ctnnb1 male tumours, including Ccne1 and Cdk1." (PMID 33214683, 2021). "Considering the most representative variants shared by tumor fragments and plasma of dogs, we identified important gene variations in ATM (C > A mutation), CCNE1 (G > C), FGFR4 (C > T), and GATA3 (G > A and C > CT)." (PMID 34680380, 2021). "To investigate the specific kinase and phosphorylation site regulating NF90’s function in cyclin E1 expression and tumor progression, we analyzed the predicted phosphorylation sites of NF90." (PMID 32123579, 2020). "The mean percentage positive tumour cells was significantly higher in CCNE1 high‐level amplified compared to non‐amplified cases; 61.2% (95% CI 54.4–68.1%) versus 33.3% (95% CI 30.9–35.7%), p < 0.0001." (PMID 32391646, 2020). "In vitro work has demonstrated that CCNE1 amplified tumours are sensitive to CDK2 or proteasome inhibition." (PMID 32391646, 2020). "Dariush Etemadmoghadam showed the specific sensitivity of proteasome inhibitor bortezomib to CCNE1-amplified tumor cells." (PMID 33194720, 2020). "RB1 and CHEK2 act as tumor suppressors, maintaining the cell in G1, whereas CCNE1 (cyclin E1) acts as an oncogene when mutated or abnormally activated." (PMID 33396315, 2020). "Three candidate miRNAs (miR-154, miR-339, and miR-34a) were predicted to target CCNE1 and circDENND2A, which acted as tumor inhibitors." (PMID 33033491, 2020). "Next we tried to determine the optimal cut‐off for percentage positive tumour nuclei by IHC to predict CCNE1 high level amplification by CISH." (PMID 32391646, 2020). "We show that this combination induces tumor regression that is durable not only in acquired PAPRi-resistant but platinum-resistant PDX models with CCNE1 amplification overcoming multiple mechanism of resistance." (PMID 32709856, 2020). "Discordant cases were reviewed and for subsequent scoring it was decided that a combination of at least 60% positive tumour cells with at least 5% strongly staining cells is considered CCNE1 overexpression (CCNE1hi)." (PMID 32391646, 2020).
tumor (continued). "The optimal cut‐off for IHC to predict CCNE1 high‐level amplification was 60% positive tumour cells with at least 5% strong staining cells (sensitivity 81.6%, specificity 77.4%)." (PMID 32391646, 2020). "In turn, massive DNA damage will accumulate in CCNE1 amplified cells and genomic instability will lead to preferential cell death in tumor cells." (PMID 32380689, 2020). "There was a striking decrease of Cyclin D1 and Cyclin E1 protein expression in the NanoTLZ treated tumor lysates, indicating cell cycle arrest." (PMID 31534547, 2019). "Gene expression analysis from baseline tumor tissues of the patients from the PALOMA-3 trial revealed that palbociclib efficacy was lower in patients who had higher CCNE1 mRNA expression in metastatic tissue." (PMID 31852484, 2019). "The results showed that CYCLIN E1 increased tumor volume and SPOP expression greatly repressed it; importantly, SPOP expression reversed the effect caused by CYCLIN E1 overexpression (left)." (PMID 30237511, 2019). "Our findings further direct Cyclin E1 signaling to tumor microenvironment and notably, the immune checkpoint signaling." (PMID 31657115, 2019). "This positive effect on tumor growth involves activation of c-myc and cyclin E1/CDK2 and their effect on cell cycle distribution." (PMID 30675171, 2019). "CCNE1 is considered to be an oncogene and is located on the chromosome 19q12, and amplification at 19q12 has been observed in multiple tumor types including gastric cancer." (PMID 31072916, 2019). "And Immunohistochemistry (IHC) assay was performed to assess the expressions of CCNE1/2 and Yap1 proteins in the tumor tissues from the model." (PMID 31455378, 2019). "This demonstrated that the tumor inhibitory efficacy of regorafenib and sorafenib is mainly mediated by cyclin E1 expression in HCC cells." (PMID 31349793, 2019). "Our in vivo data further suggested that the combination of regorafenib with cyclin E1 inhibition achieved better therapeutic effects by increasing HCC tumor apoptosis." (PMID 31349793, 2019). "Fifty-five patients were recruited in the present study, and the expression of CCNE1 in GC tissues and adjacent tissues were detected by qRT-PCR and representative four pairs of tumor and adjacent tissues were detected by Western blot." (PMID 31072916, 2019). "Nevertheless, these finding provided the rationale for the development of therapeutic approach that specifically exploit the tumor dependence upon CCNE1 amplification, for instance by targeting CDK2 and AKT activities." (PMID 31491988, 2019). "Obviously, the immunostaining intensity of CCNE1 in tumor tissues were higher than that in adjacent tissues." (PMID 31072916, 2019). "The CDK1/2/9 inhibitor AZD5438 had superior anti-tumor activity in two models with higher copy number of CCNE1." (PMID 29433585, 2018). "This notion predicts that tumor cells overexpressing cyclin E1 should need high level of CDK12 and/or cyclin K to sustain high rate of proliferation." (PMID 29760377, 2018). "CCNE1 overexpression is positively correlated with poor overall survival, even after adjustment for tumor stage." (PMID 29389895, 2018). "Of note, recent whole-genome sequencing studies of human high-grade serous ovarian carcinoma (HGSC) indicate that cyclin E1 overexpression is the driving force of tumor initiation and progression in about 30% of patients." (PMID 29760377, 2018). "Cyclin E1−/−/E2−/− mice stopped tumour cell proliferation in clonogenic assays, while the individual function of cyclin E subtypes was resolved in hepatocyte-specific NEMO and global CCNE1 or CCNE2 knockout mice." (PMID 30185601, 2018). "Analysis of a tumor sample collected from a patient with BRCA–wild-type/LOH-low genotype who had a complete response to rucaparib showed amplification of cyclin E1 (CCNE1), which is able to suppress BRCA1 expression." (PMID 30518089, 2018).
tumor (continued). "Cyclin E1 (CCNE1) expression was significantly higher in all tumour types vs controls while Cyclin D1 (CCND1) gene expression was higher in all tumour types except prolactinomas and ACTH-secreting tumours when compared to control RNA." (PMID 28649092, 2017). "This is consistent with TCGA results demonstrating significant CCNE1 (19q12) amplification in nearly 22% of the ‘serous-like/cluster 4’ tumours." (PMID 27582547, 2017). "We evaluated matched pre- vs. post-neoadjuvant chemotherapy tumor samples and correlated the degree of pathological response to treatment with CCNE1 expression levels." (PMID 28977941, 2017). "NEIL2 is located at 8p23.1, a region that has been linked to tumorigenesis and patient prognosis; CCNE1 is located at 19q12, and its amplification has been shown to promote tumor cell proliferation." (PMID 28603669, 2017). "Xenograft assay also showed that depletion of CDCA2 suppressed tumor growth in vivo with decreased expression of CCNE1." (PMID 28423619, 2017). "As ARID2 repression is closely correlated with cell proliferation and invasiveness, the expression of cell growth and aggressiveness markers Ki-67, E2F1, cyclin D1, and cyclin E1 were then evaluated in tumor tissues." (PMID 27351279, 2016). "Among these patients, Patient 5 exhibited a large increase in CCNE1 expression in tumor tissue, but the remainder of YAP target genes were either downregulated or remained unchanged." (PMID 27605415, 2016). "For example, a recent synthetic lethality screen suggested a mechanistic explanation of mutual exclusivity between CCNE1 amplification and BRCA1/2 mutation, and further showed the sensitivity of CCNE1-amplified tumor cells to bortezomib." (PMID 27558154, 2016). "We identified that 267 FFLs were dysregulated in at least one tumor type, among them E2F1_hsa-miR-195-5p_CCNE1 was most frequently disrupted in nine tumor types." (PMID 26655252, 2016). "BRCA1, being a tumour suppressor and a regulator of DNA-damage repair, has a reciprocal role to CCNE1 whose overactivation accelerates cell divisions and confers replication stress and genomic instability." (PMID 26427375, 2015). "miR-16 has multiple cell proliferation targets, such as Cyclin D1 and Cyclin E1; supporting the premise that it is a tumor suppressor miRNA." (PMID 26440311, 2015). "The analytical sensitivity of the MLPA-seq for detection of focal amplifications was tested in 14 snap-frozen tumour or FFPE tumour samples from 12 tumours with known CCNE1 or ERBB2 amplifications, originally detected with ISH assays." (PMID 26569395, 2015). "It has been proven to mediate ubiquitin-dependent proteolysis of several well-known oncoproteins including Notch, cyclin E1 and mTOR, and regarded as a tumor suppressor at the crossroads of cell division, growth and differentiation." (PMID 25749036, 2015). "Low ALDH2, high CCNE1 and SMAD3 were significantly associated with increase in tumor depth (T1, T2 and T3; P <0.05, chi-square test)." (PMID 25408144, 2014). "In the cases with amplification, fluorescence in situ hybridization for HER2 verified gene amplification and immunohistochemistry for HER2, EGFR and CCNE1 verified the overexpression of proteins in tumor cells." (PMID 25372287, 2014). "In cases with amplification, IHC for HER2, EGFR and CCNE1 showed overexpression of proteins in the tumor cells." (PMID 25372287, 2014). "These agents were synergistic with CDK4/6 inhibition, blocked the aberrant upregulation of Cyclin E1, and yielded potent inhibition of tumor cell growth." (PMID 25156567, 2014).
tumor (continued). "Unexpectedly, analysis of the data indicated that key effectors of the cell cycle like cyclin D1, cyclin E1, growth arrest and DNA damage, and cullin 1, were the primary targets of the transcriptional modifications imposed on these tumor cells." (PMID 23646174, 2013). "Ectopic over expression of CCNE1 resulted in reduced sensitivity of the MM tumor cells in comparison to the paternal cell line, whereas CCNE1 silencing with siRNA increased the cell sensitivity to seliciclib." (PMID 22558078, 2012). "Taken together, these data provide evidence that tumours harbouring 19q12 amplification have more than one 'driver' and suggest that cancer cells with CCNE1 amplification depend on CDK2 expression and kinase activity for their survival." (PMID 22433433, 2012). "Notwithstanding the prognostic value of CCNE1, its significance as a single event in the progression of a neoplasm needs to be established." (PMID 22558078, 2012). "Deregulation of cell cycle control is thought to be a prerequisite for tumor development, and several studies have shown an accelerated entry into S phase because of constitutive expression of CCNE1." (PMID 22355333, 2012). "It is possible that the biological consequence of 19q12 amplification is not limited to over-expression of CCNE1, and that other genes in the amplicon contribute to tumor growth or progression." (PMID 21103391, 2010). "Moreover, decreasing m6A has demonstrated potential therapeutic efficacy through the regulation of the YAP/CCNE1, HDGF, and cAMP pathways, which are commonly associated with tumor proliferation." (PMID 40136363, 2025). "The correlations of WGD with DSB rate, chromosome fusions, and ecDNAs may be explained by the enrichment of CCNE1 amplification in FBI tumours." (PMID 40155604, 2025). "Furthermore, we established xenograft tumor mouse models by subcutaneous injection of MDA-MB-231 cells with CCNE1 overexpression and ANLN knockdown." (PMID 40346052, 2025). "Additionally, mTOR pathway inhibitors, such as everolimus and vistusertib, have been reported to reduce tumor growth in CCNE1-amplified ovarian xenografts and increase their sensitivity to PARP inhibitors." (PMID 41331376, 2025). "Likewise, CAF-derived exosomal lncRNA maternally expressed 3 (MEG3) binds miR-15a-5p in small cell lung cancer (SCLC) cells, derepressing cyclin E1 (CCNE1) to drive cisplatin chemoresistance and tumor progression." (PMID 41409273, 2025). "Similarly, INX-315, a next-generation CDK2 inhibitor, induced cell cycle arrest and senescence in CCNE1-amplified cancer models with durable tumor control." (PMID 41331376, 2025). "CRISPR-mediated CCNE1 perturbation and patient-derived endometrial xenograft models could clarify the effects of CCNE1 on tumor growth, immune infiltration, and sensitivity to CDK2 or WEE1 inhibitors." (PMID 41331376, 2025). "FBXW7, a well-characterized tumor suppressor, mainly functions by promoting the degradation of oncogenic regulators involved in cell cycle progression and cellular differentiation, such as cyclin E1, c-Myc, c-Jun and Notch." (PMID 40721413, 2025).
tumor (continued). "Notably, CCNE1 expression was predominantly observed in 51.5% (17 of 33) of the tumor tissues, in stark contrast to the mere 5.7% (2 of 35) positivity in corresponding normal tissues (P < 0.01)." (PMID 40346052, 2025). "RP-6306 at 5 mg/kg or 10 mg/kg with RP-3500 (5 mg/kg) resulted in significant tumor regressions compared to RP-6306 monotherapy at 10 mg/kg (P = 0.0240, P = 0.0025, respectively) and RP-3500 monotherapy in the CCNE1 amp EMCA model (WU-115) model (P = 0.0032, P = 0.002, respectively)." (PMID 40169546, 2025). "But interestingly, we found that the conserved structure of CCNE1 protein exists in different types of tumor tissues, which also implies that CCNE1 may have a similar mechanism in the action of CCNE1 in tumor tissues." (PMID 39591374, 2024). "While these analyses are limited by extraction from bulk RNA sequencing, they suggest that CCNE1-amplified EGC may have a unique tumor-immune microenvironment that should be explored." (PMID 38717153, 2024). "Furthermore, innovative therapeutic approaches focusing on the downregulation of CCNE1 have shown promise in mitigating tumor growth and enhancing treatment efficacy." (PMID 39591374, 2024). "Preclinical studies identified CIC::DUX4 to molecularly depend on cell cycle mediators CCNE1 and WEE1 with CCNE1 being established as a direct transcriptional target of CIC::DUX4 that drives tumor growth and survival through an acquired dependence on CCNE/CDK2 complex." (PMID 38882060, 2024). "Similarly, the expression of CCNE1 was negatively correlated with tumour‐specific survival (p = 0.0058)." (PMID 39648148, 2024). "In addition, there is also an opportunity for synthetic lethality, particularly in CCNE1-amplified tumours that are addicted to CDK2-dependent pathways." (PMID 38732271, 2024). "Many studies of other tumor types show that CCNE1 gain is a key marker of poor prognosis that may dictate more aggressive clinical management." (PMID 39062773, 2024). "Therefore, this study provided a lead compound for antitumor drugs, especially those against CCNE1-amplified tumor proliferation." (PMID 38338471, 2024). "According to the expression level of CCNE1, the tumor cases were divided into high and low groups." (PMID 39591374, 2024). "Tumours with high nuclear cyclin E1/high nuclear CDK2 have a worse PFS and OS." (PMID 38612869, 2024). "In sum, AURKB promoted CRC tumor growth through its activation of CCNE1 in vivo." (PMID 38713155, 2024). "Tumours with high nuclear cyclin E1/high nuclear CDK2 also had a worse PFS and OS." (PMID 38612869, 2024). "Whilst WEE1 inhibition may be a useful means of treating tumours with CCNE1 overexpression, identifying novel synthetic lethality targets through genome wide screens may highlight alternative strategies." (PMID 39135999, 2024). "In order to test the oncogenic activity of LINC01116, miR‐9‐5p and CCNE1 in vivo, LUAD cells stably expressing sh‐LINC01116 and overexpressing miR‐9‐5p or CCNE1 stably were subcutaneously injected into the subcutaneous tissue of nude mice, establishing the xenograft tumour model." (PMID 39648148, 2024). "Thus, we first treated Ccne1+ tumor-bearing immunocompetent mice (immune-excluded, chemo-resistant model) with a standard regimen of doxorubicin (DOX) (6 mg/kg), alone or in combination with the GLUT1 inhibitor (GLUT1i, BAY-876, 5 mg/kg)." (PMID 38509063, 2024). "Two significant pathways, hsa04080, Neuroactive ligand-receptor interaction, and hsa04950, Maturity onset diabetes of the young (MODoY; with transcription factors FOXA3, NKX6-1, MAFA, PAX6, PDX1), were identified for the genes expressed more highly in the high-CCNE1 tumours." (PMID 38612869, 2024).